S100A2 (S100 calcium binding protein A2)
Diseases named in the same sentence as S100A2 in open-access papers (continued):
Sharing a sentence is not in itself a finding about the gene and the disease.
bladder cancer (4 papers, 2015 to 2024). "In summary, we have demonstrated aberrant S100A2 gene methylation in human head&neck and bladder cancer and most importantly promoter methylation of S100A2 is inversely associated with gene expression." (PMID 26097874, 2015). "We show that loss of S100A2 expression in head and neck and bladder cancer cell lines is associated with the methylation of CpG islands and can be restored with 5-aza-2′-deoxycytidine treatment." (PMID 26097874, 2015). "S100A2 is associated with the development of bladder cancer in vivo." (PMID 35885660, 2022). "Together, this data shows that methylation-associated inactivation of S100A2 is frequent and may be an important event in the tumorigenesis of head&neck and bladder cancer." (PMID 26097874, 2015). "Moreover, increased methylation of S100A2 is linked to the progression of the tumor in bladder cancer (p<0.01)." (PMID 26097874, 2015). "Decreased expression of S100A2 is related to tumor progression and unfavorable clinical outcomes in patients with bladder cancer in vivo." (PMID 35885660, 2022). "S100A2 promoter methylation can be detected in urine and is more frequent in bladder cancer patients than in healthy subjects (96% vs 48% respectively)." (PMID 26097874, 2015). "Here, we investigated the expression and methylation status of S100A2 in head&neck and bladder cancer." (PMID 26097874, 2015). "We have found aberrant methylation involving the promoter regions of S100A2 in different histologies of head&neck and bladder cancer." (PMID 26097874, 2015). "Using RT-PCR and Western blotting, we analyzed the expression patterns of S100A2 in 14 established head&neck and bladder cancer cell lines." (PMID 26097874, 2015). "In this study, we examined the status of 5′CpG island methylation of S100A2 in head&neck and bladder cancer." (PMID 26097874, 2015). "Here, we investigated if hypermethylation of S100A2 can be detected in urine samples of bladder cancer cases." (PMID 26097874, 2015). "This may suggest that S100A2 promoter methylation is a common event in bladder cancer and it can be detected in urine." (PMID 26097874, 2015). "Therefore, application of S100A2 methylation for detection of head&neck and bladder cancers requires further evaluation." (PMID 26097874, 2015). "To investigate whether S100A2 methylation could be potentially utilized for detection of bladder cancer, we investigated S100A2 methylation status in DNA isolated from urine samples." (PMID 26097874, 2015). "To determine whether S100A2 promoter methylation was limited to cultured head&neck and bladder cancer cell lines, we examined the promoter methylation of S100A2 in primary head&neck and bladder cancers." (PMID 26097874, 2015). "In addition, our findings of significantly high frequency of S100A2 methylation in primary head&neck and bladder cancer support the fact that epigenetic silencing of this gene may be a tumor-specific event." (PMID 26097874, 2015). "S100A2 expression was absent in four head and neck cancer cell lines (011, 012, 022, and 028) and all four bladder cancer cell lines (5637, HT1376, J82, and SCaBER)." (PMID 26097874, 2015).
esophageal cancer (4 papers, 2015 to 2024). A primary or metastatic malignant neoplasm involving the esophagus. "As a candidate tumor suppressor protein, the expression of S100A2 is significantly lower in a variety of malignancies, such as breast, liver, prostatic, and esophageal cancer." (PMID 26106439, 2015).
head and neck cancer (4 papers, 2004 to 2024). A primary or metastatic malignant neoplasm affecting the head and neck. "Therefore, it seems that loss of S100A2 might be an important event in tumor progression towards more malignant cell phenotype in head and neck cancer, but the decrease in its level may be also attributed to loss of epithelial phenotype." (PMID 26097874, 2015). "While our report provides a thorough examination of the expression of S100A2 in head&neck and bladder, it should be noted that previous reports on the expression of S100A2 in head&neck cancer have been contradictory." (PMID 26097874, 2015). "Conversely, in addition to our analysis of NSCLC, over-representation of S100A2 has also been reported in gastric cancer ovarian cancer and head and neck cancer." (PMID 15467767, 2004).
laryngeal squamous cell carcinoma (4 papers, 2008 to 2022). A squamous cell carcinoma that arises from the larynx. "S100A2 expression in laryngeal squamous cell carcinoma is positively correlated with longer relapse-free and overall survival." (PMID 35885660, 2022). "Another study found this gene to be expressed in more than 95% of low-grade tumors and 51% of high-grade tumors of laryngeal squamous cell carcinoma, however S100A2 negative cases were typically anaplastic non-keratinizing tumors that generally bear more malignant characteristics." (PMID 26097874, 2015).
pulmonary fibrosis (4 papers, 2022 to 2025). Chronic progressive interstitial lung disorder characterized by the replacement of the lung tissue by connective tissue, leading to progressive dyspnea, respiratory failure, or right heart failure. "A recent study aligns intriguingly with our findings, demonstrating elevated expression of S100A2 in patients with pulmonary fibrosis." (PMID 39382800, 2024).
Alzheimer disease (3 papers, 2007 to 2024). A progressive, neurodegenerative disease characterized by loss of function and death of nerve cells in several areas of the brain leading to loss of cognitive function such as memory and language. "The age- and disease-associated loss of S100A2 DNA methylation in Alzheimer's disease is consistent with the observation of S100A2 protein in corpora amylacea, or polyglucosan bodies, which accumulate in aging human brains." (PMID 17878930, 2007). "Alzheimer’s disease (AD) has been shown to present a statistically significant difference in DNA methylation for S100A2." (PMID 34746237, 2021). "Therefore, the significant DNA methylation changes in Alzheimer's disease, including the decrease of S100A2 and increase in SORBS3 CpG methylation, appear to represent accelerations of the normal, age-associated DNA methylation changes in these genes." (PMID 17878930, 2007). "The miR-26b-5p has been reported to be involved in mitochondrial dynamics and predicted to be a specific biomarker of Alzheimer’s disease, but the effect on NEAT1 or S100A2 has not yet been studied." (PMID 39739972, 2024).
breast tumors (3 papers, 2015 to 2019). "During breast tumorigenesis and/or progression, several S100 s, including S100A2, S100A4 and S100A7, exhibit altered expression levels based on molecular analysis of breast tumors." (PMID 31795964, 2019). "Recent studies indicated that abnormal expression of S100 proteins – mainly including S100A2, S100A4, and S100A7 – is related to metastasis of breast tumor." (PMID 31244288, 2019). "Protein biomarkers such as S100A2, OAS2 and/or IFNβ RNA expression in breast tumors may prove to be useful guides in predicting the response of IFN-positive patients to anti-interferon therapeutics." (PMID 25884794, 2015).
inflammatory skin disease (3 papers, 2021 to 2022). Inflammatory skin disorders covers a broad category that includes many conditions ranging in severity, from mild itching to grave medical health complications These disorders are common in people of all ages and races. "An important finding is that the degree of S100A2 expression depends on the severity of inflammatory skin diseases." (PMID 35885660, 2022). "Consistently the SCORAD score, a scale of the severity of AD, was significantly and positively correlated with S100A2 expression, indicating that S100A2 is involved in representative inflammatory skin diseases." (PMID 33750880, 2021). "S100A2 expression was upregulated in patients with severe-type drug eruptions and other inflammatory skin diseases." (PMID 33750880, 2021). "The actual impact of S100A2 on inflammatory skin diseases remains unclear; however, our public microarray data sets revealed that S100A2 is possibly involved in the pathogenesis of inflammatory skin diseases." (PMID 33750880, 2021). "Furthermore, S100A2 overexpression in the epidermis was also observed in other representative inflammatory skin diseases and correlated with the severity of AD." (PMID 33750880, 2021). "Furthermore, we found S100A2 overexpression in the epidermis of patients with other inflammatory skin diseases, suggesting the role of S100A2 as a marker of keratinocyte damage in response to any inflammatory and toxic condition." (PMID 33750880, 2021). "On the contrary, S100A2 might play a regulatory role in the inflammatory response by mediating a negative feedback effect on inflammatory skin diseases." (PMID 33750880, 2021).
oral squamous cell carcinoma (3 papers, 2020 to 2024). "Studies of patients with oral squamous cell carcinoma also indicate that S100A2 is related to tumor recurrence in vivo." (PMID 35885660, 2022). "S100A2 in saliva has been proposed as a candidate biomarker for the early detection of oral squamous cell carcinomas in humans and S100A11 is overexpressed in several human cancers tissues, although to the author’s knowledge there are no reports that evaluate these two proteins in DM in humans." (PMID 33271797, 2020). "A high frequency of metastasis is found in patients with S100A2-negative oral squamous cell carcinoma tumors in vivo." (PMID 35885660, 2022).
benign breast tumour (2 papers, 2000 to 2002). "A suppression subtraction cDNA library representing mRNAs expressed at a higher level in a benign breast tumour-derived cell line relative to the malignant MCF-7A cell line contained cDNAs corresponding to mRNAs for plasminogen activator inhibitor I, annexin VIII and the EF-hand protein S100A2." (PMID 11076656, 2000).
bladder tumor (2 papers, 2015 to 2021). "Using QMSP, we examined the methylation status of S100A2 in 31 head and neck and 31 bladder tumor tissue samples as well as in 15 normal tissue samples from the head and neck and bladder." (PMID 26097874, 2015). "Results presented here showed that frequency of hypermethylation of S100A2 is significantly higher in urine samples from bladder tumor cases than in healthy subjects (96% vs 48% respectively)." (PMID 26097874, 2015). "However, only the S100A2 expression was verified in human bladder tissues and showed significance between bladder tumor and normal tissues." (PMID 34568039, 2021). "Furthermore, we demonstrate high frequency of aberrant methylation of S100A2 in primary head&neck and bladder tumor samples." (PMID 26097874, 2015).
brain tumors (2 papers, 2021 to 2022). "However, the role of S100A2 and S100A3 in brain tumors has been less well studied." (PMID 34148033, 2021).
carcinoma in situ (2 papers, 2000 to 2022). "S100A2 mRNA was detectable in 37% of specimens of carcinoma in situ, but in less than 15% of carcinoma specimens." (PMID 11076656, 2000).
cholangiocarcinoma (2 papers, 2015 to 2022). A carcinoma that arises from the intrahepatic biliary tree (intrahepatic cholangiocarcinoma) or from the junction, or adjacent to the junction, of the right and left hepatic ducts (hilar cholangiocarcinoma). "S100A2 expression in cholangiocarcinoma cells is related to a high frequency of lymph node metastasis, advanced clinical stage, and poor patient survival rates in vivo." (PMID 35885660, 2022). "However, the biological function of S100A2 in cholangiocarcinoma remains to be elucidated." (PMID 25999659, 2015).
dysplasia (2 papers, 2004 to 2015). A usually neoplastic transformation of the cell, associated with altered architectural tissue patterns. "As the degree of tissue disorder increased, so did the frequency with which lesions stained for S100A2 with: 16% (nine out of 55) of hyperplastic and 62% (eight out of 13) of preneoplastic (metaplasia, dysplasia, CIS) lesions showing strong nuclear staining (P<0.0001)." (PMID 15467767, 2004).
endometrial carcinoma (2 papers, 2022). A malignant tumor arising from the epithelium that lines the cavity of the uterine body. "The results showed that patients with high S100A2 mRNA expression levels had worse OS and DSS, while multivariate Cox analysis confirmed that high S100A2 expression was an independent risk factor for OS in individuals with endometrial carcinoma." (PMID 35042454, 2022). "Next, we sought to identify the putative cellular mechanisms underlying the effects of S100A2 in endometrial carcinoma through KEGG pathway analysis and GSEA." (PMID 35042454, 2022). "Multivariate Cox analysis further confirmed that high S100A2 expression was an independent risk factor for OS in patients with endometrial carcinoma." (PMID 35042454, 2022). "S100A2 plays an important role in endometrial carcinoma progression and may represent an independent diagnostic and prognostic biomarker for endometrial carcinoma." (PMID 35042454, 2022). "Our results suggested that S100A2 may be a promising diagnostic and prognostic biomarker for endometrial carcinoma." (PMID 35042454, 2022). "Subsequently, the Kaplan–Meier plotter and Cox regression analysis were used to assess the prognostic significance of S100A2, while the association between S100A2 expression and clinical characteristics in endometrial carcinoma was also analyzed using logistic regression." (PMID 35042454, 2022). "Importantly, ROC analysis also confirmed that S100A2 has a high diagnostic value in endometrial carcinoma." (PMID 35042454, 2022). "We further investigated the relationship between clinical characteristics and S100A2 mRNA expression in endometrial carcinoma patients and found that high S100A2 expression was associated with clinical stage and menopause status." (PMID 35042454, 2022). "GSEA analysis revealed that S100A2 interacts with the IL-17 signaling pathway in endometrial carcinoma." (PMID 35042454, 2022). "Subsequently, a nomogram was constructed using age, clinical stage, histologic grade, tumor invasion, histological type and S100A2 levels as indicators to predict 1-, 3-, and 5-year OS in patients with endometrial carcinoma." (PMID 35042454, 2022). "The protein expression level of S100A2 was also upregulated in endometrial carcinoma tissues in comparison with normal tissues, indicating that the protein and mRNA expressions of S100A2 were similar in different database." (PMID 35042454, 2022). "S100A2 expression was also upregulated in serous type of endometrial carcinoma compared with that in endometrioid type disease (P = 0.02)." (PMID 35042454, 2022). "In conclusion, this analysis revealed that S100A2 was more highly expressed in endometrial carcinoma tissues than in normal tissues and was correlated with worse survival." (PMID 35042454, 2022). "We further investigated the prognostic value of S100A2 in endometrial carcinoma using Kaplan–Meier plotter." (PMID 35042454, 2022). "Patients with endometrial carcinoma with high S100A2 expression exhibit poor overall survival and disease-specific survival in vivo." (PMID 35885660, 2022). "Univariate logistic regression analysis demonstrated that S100A2 expression was correlated with some clinical characteristics in patients with endometrial carcinoma." (PMID 35042454, 2022). "The results showed that S100A2 mRNA expression levels were significantly higher in endometrial carcinoma primary tumor samples than in normal tissue (P < 0.05)." (PMID 35042454, 2022). "Although the current study revealed a potential interaction between S100A2 and the IL-17 signaling pathway, how S100A2 precisely regulates endometrial carcinoma progression requires further investigation." (PMID 35042454, 2022). "Although increased levels of estrogens in the blood are believed to encourage the development of endometrial cancer, the crosstalk between estrogen and S100A2 remains poorly understood." (PMID 35042454, 2022). "S100A2 has potential as a prognostic factor for patients with endometrial carcinoma." (PMID 35042454, 2022).
endometrial carcinoma (continued). "Here, we found that S100A2 also has prognostic significance for endometrial carcinoma." (PMID 35042454, 2022). "S100A2 expression is upregulated in endometrial carcinoma tissues in vivo." (PMID 35885660, 2022). "Collectively, these findings demonstrated that S100A2 may be a promising biomarker for the diagnosis of endometrial carcinoma." (PMID 35042454, 2022). "Moreover, multivariate regression analysis further confirmed that S100A2 expression was an independent prognostic factor for OS in patients with endometrial carcinoma (HR = 1.635, 95% CI = 1.005-2.659, P = 0.048)." (PMID 35042454, 2022). "Additionally, S100A2 expression was significantly upregulated in 23 endometrial carcinoma samples when compared with that in matched adjacent samples (P = 3.3e−06)." (PMID 35042454, 2022). "Our study provides new insights regarding the contribution of S100A2 to endometrial carcinoma progression and may be of empirical value for future investigations on inhibitors targeting S100A2 for the treatment of endometrial carcinoma." (PMID 35042454, 2022). "However, little is known about the clinical significance of S100A2 in endometrial carcinoma." (PMID 35042454, 2022). "High S100A2 expression has been associated with the regulation of tumor cell proliferation and invasion through the enhancement of PI3K/AKT activation and functional interaction with SMAD3; however, whether S100A2 expression has prognostic value in endometrial carcinoma has remained unknown." (PMID 35042454, 2022). "Our results revealed that S100A2 expression was significantly higher in endometrial carcinoma tissue than in non-cancerous tissue at both the mRNA and protein levels." (PMID 35042454, 2022).
head and neck squamous cell carcinoma (2 papers, 2015). A squamous cell carcinoma that arises from any of the following anatomic sites: lip and oral cavity, nasal cavity, paranasal sinuses, pharynx, larynx, and salivary glands. "In head and neck squamous cell carcinoma, S100A2 expression was noted in some primary tumors, lymph node metastasis showed reduction in staining." (PMID 26097874, 2015). "Studies of head and neck squamous cell carcinoma show variable levels of S100A2 in different cell lines." (PMID 26097874, 2015).
hepatocellular carcinoma (2 papers, 2022). A malignant tumor that arises from hepatocytes. "Hepatocellular carcinoma (HCC) is a representative common hepatic cancer, and S100A2 is highly expressed and associated with advanced clinical features in HCC patients in vivo." (PMID 35885660, 2022).
kidney cancer (2 papers, 2021 to 2022). Primary or metastatic malignant neoplasm involving the kidney. "Renal cell carcinoma is the most common kidney cancer in adults, and S100A2 expression is decreased due to the DNA methylation of the promoter site of S100A2 in vitro." (PMID 35885660, 2022).
medulloblastoma (2 papers, 2007 to 2021). A malignant, invasive embryonal neoplasm arising from the cerebellum. "For example, DNA hypomethylation resulted in reduced S100A6 and S100A10 expression in medulloblastoma while somatic methylation controlled S100A2 and S100A4 expression in the normal cerebellum, showing tissue specific regulation." (PMID 34485305, 2021). "The methylation status of CpG sites within the promoter/exon 1 regions of S100A6 and S100A2, which have previously been identified as being involved in their epigenetic regulation, was established in a panel of nine medulloblastoma cell lines by bisulphite sequencing." (PMID 17579622, 2007). "Assessment of these genes in the non-neoplastic cerebellum (from which medulloblastomas develop) revealed strong somatic methylation affecting S100A2 and S100A4, whereas S100A6 and S100A10 were unmethylated." (PMID 17579622, 2007).